NPSR1 (neuropeptide S receptor 1)
Diseases named in the same sentence as NPSR1 in open-access papers (continued):
Sharing a sentence is not in itself a finding about the gene and the disease.
substance abuse (2 papers, 2021 to 2025). The use of a drug for a reason other than which it was intended or in a manner or in quantities other than directed. "However, the possible implications of the NPS/NPSR1 system, especially those of the single nucleotide polymorphism (SNP) rs324981, in stress-related disorders and substance abuse in humans remain unclear." (PMID 34451877, 2021). "Another example is GPR154, currently named neuropeptide S receptor 1 (NPSR1), which appears to regulate behaviours related to substance abuse and cognitive functions and was associated with the pathophysiology of multiple diseases." (PMID 40534243, 2025). "As reviewed, there is substantial clinical and preclinical evidence for a role of the NPS/NPSR1 system in the behavioural and emotional changes relevant to stress-related disorders and substance abuse." (PMID 34451877, 2021).
adenocarcinoma of the lung (1 paper, 2024). "Gene NPSR1 promotes the malignant phenotype of adenocarcinoma of the lung and thyroid cancer cells, and Ano2 is associated with multiple sclerosis." (PMID 38891594, 2024).
agoraphobia (1 paper, 2024). An anxiety disorder characterized by an intense, irrational fear of venturing out into open places or situations in which help (or escape) might not be available should excessive anxiety or panic symptoms develop. "In the second one, the association of the NPSR1 T-risk allele with malfunctioning in the front-limbic network during anticipation and perception of agoraphobia-specific stimuli in PD/AG patients and HCs was explored." (PMID 39025836, 2024).
colitis (1 paper, 2018). Inflammation of the colon. "While LYZ has been associated with colitis, and S100P associated with the progression of colitis-associated dysplasia, neither LYZ nor NPSR1 had been shown to be associated with CAC." (PMID 29983891, 2018). "Further, we have extended these findings and confirmed the presence of these signatures at the protein level in CAC organoids and tissues, demonstrating increased expression of LYZ and S100P in both colitis and CAC, and increased expression of NPSR1 in colitic organoids and tissues." (PMID 29983891, 2018).
colon cancer (1 paper, 2014). "Endogenous expression of NPSR1 in cultured cells is low with the exception of human Colo205 colon cancer cells." (PMID 24915894, 2014).
colorectal adenocarcinoma (1 paper, 2014). The most common type of colorectal carcinoma. "To study whether expression of NPSR1 is specific for NETs or a general marker of abnormal growth, we compared the expression of NPSR1 in colorectal adenocarcinomas (n = 25) and NETs." (PMID 24915894, 2014). "Our results show that the expression of NPS/NPSR1 is specific for NETs as NPSR1 was expressed in the NETs of the GI tract but not in colorectal adenocarcinoma samples from the same primary site." (PMID 24915894, 2014).
Hypertension (1 paper, 2021). The presence of chronic increased pressure in the systemic arterial system. "After 12 weeks of EOJ consumption, four genes related to hypertension (PTX3, NLRP3, NPSR1 and NAMPT) were differentially expressed in peripheral blood mononuclear cells (P < 0.05)." (PMID 32661681, 2021).
insomnia (1 paper, 2023). A sleep disorder characterized by difficulty in falling asleep and/or remaining asleep. "Notwithstanding, SNPs such as rs10493596, rs2302729, rs12927162, rs324957/rs324981, and rs1823125 in genes AK5, CACNA1C, TOX3, neuropeptide S receptor (NPSR1), and PAX8, respectively contribute to insomnia symptoms." (PMID 37163444, 2023).
paraganglioma (1 paper, 2014). A benign or malignant neoplasm arising from paraganglia located along the sympathetic or parasympathetic nerves. "Pheochromocytomas of the adrenal medulla showed no or only very low immunoreactivity for NPSR1 and NPS whereas extra-adrenal sympathetic paragangliomas showed stronger reactivity for the antigens." (PMID 24915894, 2014).
pheochromocytoma (1 paper, 2014). "One of our most interesting findings was that NPSR1 is expressed in sympathetic extra adrenal paragangliomas but not in pheochromocytomas arising from the adrenal medulla." (PMID 24915894, 2014).
stress-related disorder (1 paper, 2021). Stress-related disorders are mental health disorders that are a result of an atypical response to both short and long-term anxiety due to physical, mental, or emotional stress. "We have also described findings on the potential association of the NPS/NPSR1 system with pathophysiological features of stress-related disorders." (PMID 34451877, 2021). "In addition, a potential association of the NPS/NPSR1 system with pathophysiological features of stress-related disorders and substance use disorder (SUD) has recently been proposed (see for review)." (PMID 34451877, 2021). "The primary goal of this review is to highlight the importance of studying some rodent behavioural readouts modulated by the NPS/NPSR1 system and relevant to stress-related disorders." (PMID 34451877, 2021). "Despite numerous challenges inherent in developing therapeutics targeting neuropeptide systems (see for review), future pharmacological studies should, thus, consider targeting the central NPS/NPSR1 system for treating stress-related disorders." (PMID 34451877, 2021). "Given the genetic complexity at the NPSR1 locus and the functional consequences of the NPSR1 rs324981 SNP, behavioural and emotional changes relevant to stress-related disorders are currently under further investigation using this “humanized” mouse model." (PMID 34451877, 2021). "Moreover, we discuss the therapeutic potential and possible caveats of targeting the NPS/NPSR1 system for the treatment of stress-related disorders." (PMID 34451877, 2021).
tauopathy (1 paper, 2023). Neurodegenerative disorders involving deposition of abnormal tau protein isoforms (tau proteins) in neurons and glial cells in the brain. "We recently demonstrated that two familial natural short sleep (FNSS) mutations, DEC2-P384R and Npsr1-Y206H, are strong genetic modifiers of tauopathy in PS19 mice, a model of tauopathy." (PMID 37014857, 2023).
trachoma (1 paper, 2018). "NPSR1 interacts with phospholipase C and like both PRKG1 and PREX2 (the best candidate associated gene from the trachoma GWAS) is part of the G protein-mediated cascade of intracellular signalling that centres around the PI3K/Akt pathway of cell cycle regulation." (PMID 29967566, 2018).
psychiatric disorder (4 papers, 2012 to 2021). A disorder characterized by behavioral and/or psychological abnormalities, often accompanied by physical symptoms. "The vast majority of available studies describe the function of the NPS system on a network level, analyze behavioral consequences following pharmacological or genetic interventions, or point out implications of NPSR1 single-nucleotide polymorphisms for psychiatric disorders in humans." (PMID 34072275, 2021). "In turn, alterations of NPSR1 signaling efficacy by nonsynonymous mutations in the NPSR1 or the NPS gene might consequently alter behavior and the risk for the development of psychiatric disorders." (PMID 34072275, 2021).
cancer (3 papers, 2014 to 2022). A tumor composed of atypical neoplastic, often pleomorphic cells that invade other tissues. "The results from the cell line experiments indicate that stimulation of NPSR1 with NPS results in activation of pathways that are relevant for cancer development." (PMID 24915894, 2014). "In combined treatment with cisplatin, siRNAs against five genes (ADRA2A, F2RL3, NPSR1, NPY and TACR3) enhanced the anti-proliferation efficacy on cancer cells and reduced the self-recovery ability of surviving cells after the removal of the combined treatment." (PMID 36253428, 2022). "Our results show that NPS and NPSR1 are expressed in NETs, and NPS activates pathways important in cancer development." (PMID 24915894, 2014). "Our results show that NETs are a source of NPS and NPSR1, and that NPS affects cancer-related pathways." (PMID 24915894, 2014).
gastrointestinal disorders (2 papers, 2011 to 2021). "A family study on functional gastrointestinal disorders implies a genetic influence on pediatric RAP, and a population-based study showed that genetic variation in the NPSR1 gene, which codes for the neuropeptide S receptor, influences children’s predisposition to RAP." (PMID 33525537, 2021).
tumor (2 papers, 2014 to 2026). "Both in vivo and in vitro studies demonstrated that NPSR1 overexpression robustly accelerated GC cell proliferation and migration, while its silencing suppressed tumor progression." (PMID 41954778, 2026).
adenocarcinoma (1 paper, 2014). A common cancer characterized by the presence of malignant glandular cells. "NPSR1 was not expressed in the adenocarcinoma samples, but was expressed in the NETs of the GI tract (rectum, ileum), suggesting that expression of NPSR1 might be specific for NETs." (PMID 24915894, 2014).
NPSR1 also shares sentences with these, for which no sentence is quoted: Allergy (5 papers); Arthritis (2); depression (2); irritable bowel syndrome (2); alcohol dependence (1); alcohol withdrawal syndrome (1); Alzheimer disease (1); atopic dermatitis (1); autism spectrum disorder (1); cocaine addiction (1); eczema (1); emotional dysregulation (1); gastric cancer (1); hyperthyroidism (1); memory (1); metastatic tumors (1); multiple sclerosis (1); neurodegenerative disease (1); pancreas cancer (1); Parkinson (1); psoriasis (1); rectal tumor (1); respiratory distress syndrome (1); retinitis pigmentosa (1); sleep disorder (1); thyroid cancer (1); transient neonatal diabetes mellitus (1); withdrawal syndrome (1).